CD160 (CD160 molecule)
Description:
[CD160 antigen]: Receptor on immune cells capable to deliver stimulatory or inhibitory signals that regulate cell activation and differentiation. Exists as a GPI-anchored and as a transmembrane form, each likely initiating distinct signaling pathways via phosphoinositol 3-kinase in activated NK cells and via LCK and CD247/CD3 zeta chain in activated T cells. Receptor for both classical and non-classical MHC class I molecules. In the context of acute viral infection, recognizes HLA-C and triggers NK cell cytotoxic activity, likely playing a role in anti-viral innate immune response. On CD8+ T cells, binds HLA-A2-B2M in complex with a viral peptide and provides a costimulatory signal to activated/memory T cells. Upon persistent antigen stimulation, such as occurs during chronic viral infection, may progressively inhibit TCR signaling in memory CD8+ T cells, contributing to T cell exhaustion. On endothelial cells, recognizes HLA-G and controls angiogenesis in immune privileged sites. Receptor or ligand for TNF superfamily member TNFRSF14, participating in bidirectional cell-cell contact signaling between antigen presenting cells and lymphocytes. Upon ligation of TNFRSF14, provides stimulatory signal to NK cells enhancing IFNG production and anti-tumor immune response (By similarity). On activated CD4+ T cells, interacts with TNFRSF14 and down-regulates CD28 costimulatory signaling, restricting memory and alloantigen-specific immune response. In the context of bacterial infection, acts as a ligand for TNFRSF14 on epithelial cells, triggering the production of antimicrobial proteins and pro-inflammatory cytokines (By similarity). [CD160 antigen, soluble form]: The soluble GPI-cleaved form, usually released by activated lymphocytes, might play an immune regulatory role by limiting lymphocyte effector functions.
Synonyms: BY55; NK1; NK28
Tractability: Antibody: UniProt places it where antibodies can reach, with high confidence; its Gene Ontology location is reachable by antibodies, with high confidence; UniProt predicts a signal peptide or a membrane-spanning region.
Gene: Protein-coding gene on chromosome 1 (145,719,443 to 145,740,760, forward strand). Ensembl gene ENSG00000117281.
Subcellular location: Cell membrane (CD160 antigen); Secreted (CD160 antigen, soluble form)
Pathways (Reactome):
Immune System: Immunoregulatory interactions between a Lymphoid and a non-Lymphoid cell
Gene Ontology:
Molecular function: activating MHC class I receptor activity; kinase binding; MHC class I receptor activity; MHC class Ib receptor activity; protein binding; signaling receptor binding; MHC class I protein complex binding; transmembrane signaling receptor activity
Biological process: negative regulation of adaptive immune memory response; negative regulation of angiogenesis; negative regulation of CD4-positive, alpha-beta T cell costimulation; negative regulation of T cell receptor signaling pathway; phosphatidylinositol 3-kinase/protein kinase B signal transduction; positive regulation of endothelial cell apoptotic process; positive regulation of natural killer cell cytokine production; positive regulation of natural killer cell mediated cytotoxicity; T cell costimulation; immune system process; mucosal immune response; positive regulation of cytokine production; positive regulation of natural killer cell mediated immune response to tumor cell; positive regulation of natural killer cell mediated immunity; positive regulation of type II interferon production; regulation of adaptive immune response
Cellular component: plasma membrane; extracellular region
Genetic constraint (gnomAD): Loss-of-function variants: 9 observed, 17.93 expected, observed/expected ratio (o/e) 0.5, 90% interval 0.3 to 0.88. The upper end of that interval is the gene's LOEUF score, 0.88, which puts it in group 3 of 6, group 1 being the genes least tolerant of losing a copy. Missense variants: 166 observed, 208.05 expected, observed/expected ratio (o/e) 0.8, 90% interval 0.7 to 0.91. Synonymous variants: 68 observed, 76.91 expected, observed/expected ratio (o/e) 0.88, 90% interval 0.73 to 1.08.
Homologues: Orthologues: chimpanzee CD160 (99% identical), macaque CD160 (91% identical), dog CD160 (72% identical), mouse Cd160 (66% identical), rat Cd160 (64% identical).
Diseases named in the same sentence as CD160 in open-access papers:
CD160 is named in the same sentence as 100 diseases in open-access papers, as found by Europe PMC text mining. Sharing a sentence is not in itself a finding about the gene and the disease. The quoted sentences say what the papers report.
viral infection (13 papers, 2012 to 2025). "CD160 has been implicated in various conditions, including malignancies, atherosclerosis, malaria, viral infections, autoimmune disorders, and eye diseases." (PMID 38592036, 2024). "Furthermore, CD160 has been reported to be a marker for T cell exhaustion, and increased CD160 expression in CD8+ T cells is associated with T cell exhaustion in chronic viral infection models." (PMID 31332204, 2019). "However, CD160 mRNA expression has been demonstrated on exhausted CD8 T cells in the late stage of chronic viral infection, which coincides with loss of CTL function." (PMID 23593209, 2013). "Our results highlight a critical and active role of CD160 signaling in host immunity against chronic viral infection." (PMID 33072082, 2020). "Our data demonstrated that CD160 acts as a costimulatory molecule positively regulating CD8+ T cells during chronic viral infections, thus representing a potential target for immune intervention." (PMID 33072082, 2020). "To determine the functional role of CD160-expressing CD8+ T cell during chronic viral infection, we employed CD160 knockout (CD160KO) mice, which were previously used as in vivo model to study CD160 functioning in NK and NKT cells." (PMID 33072082, 2020). "Our data suggest that CD160 may be a rational target for immune intervention in chronic virus infection as triggering CD160 is likely to further enhance the therapeutic effect of PD-1 blockade." (PMID 33072082, 2020). "The lower frequencies of HIV-specific DP CD8 T cells in ECs compared to CHI subjects suggested the involvement of CD160 and PD-1 co-expression in antigen-specific T cell dysfunction as previously shown in mice models of chronic viral infection and suggested recently in HIV-infected subjects." (PMID 22916009, 2012). "Positive expression of iRs such as PD1, CTLA-4, TIM3, LAG-3, 2B4, CD160, and BTLA has been directly linked to reduced cytokine production by T cells from cancer patients (including reports from our group) or in the chronic LCMV mouse model of “T cell exhaustion” and other viral infections." (PMID 24391639, 2013). "CD160+ IEL have been reported to show a cytotoxic function, particularly in the setting of viral diseases." (PMID 39372792, 2024). "Consistently, increased levels of both CD244 and CD160 in patients infected SARS-CoV-2 and other viruses indicated that T cell aging occurred as well as exhaustion in viral infection." (PMID 35386693, 2022). "In summary, we identified CD160 primarily functioning as a costimulatory receptor molecule responsible for the optimal activation and proliferation/survival of CD8+ T cells, thus essential for virus control, during chronic virus infection." (PMID 33072082, 2020). "Second, CD160 may facilitate the escape of CD8+ T cells from terminal differentiation, maintaining a pool of durable, polyfunctional cells during chronic virus infection." (PMID 33072082, 2020). "Thus, the gene expression signature of CD160+ CD8+ T cells is consistent with their proliferative and survival capability, indicating their potential as a long-persisting source for the functional pool of CD8+ T cells during chronic virus infection." (PMID 33072082, 2020). "Furthermore, their CTLs expressed PD-1 and LAG-3, but not CD244 and CD160, at significantly higher levels than those of non-leukemic mice, a phenotype resembling exhaustion during chronic virus infection." (PMID 26658107, 2015). "It is possible that during natural bacteria or viral infections in Light−/− mice, BTLA and/or CD160 may signal through HVEM to compensate for the absence of LIGHT." (PMID 24205057, 2013).
COVID-19 (10 papers, 2021 to 2024). A disease caused by infection with severe acute respiratory syndrome coronavirus 2. "In recent years, researchers have shown that CD160 is associated with the recovery of COVID-19 patients." (PMID 36733384, 2022). "A study has shown that in mild or moderate cases of COVID-19, the number of CD160+ NKT cells increases, which is associated with a quicker resolution of the infection by direct cytotoxicity." (PMID 36034704, 2022). "The inhibition of neutrophil adhesion to endothelial cells obtained with plasma samples from survivor COVID-19 patients was significantly inhibited by anti-CD160 treatment (p < 0.001; Student’s t-test)." (PMID 34578436, 2021). "Besides, the enrichment of CASP3+CD8+CD160+ cells was observed in the lung autopsy samples of COVID-19 patients." (PMID 39414763, 2024). "Of note, all the genes associated with the apoptosis pathways were up-regulated in the SM group, indicating that (LAG3+CD160+CD8+)NKT cells may play a critical role in the pathogenesis of COVID-19." (PMID 35281000, 2022). "In moderate cases of COVID-19, an expansion of CD160+ NKT cells has been observed which may help to promote quick resolution of the infection through direct cytotoxicity." (PMID 34050887, 2022). "The inhibition of neutrophil adhesion to endothelial cells obtained with plasma samples from survivor COVID-19 patients was significantly inhibited by anti-CD160 treatment, suggesting a role of HLA-G/CD160 interaction in regulating neutrophil adhesion to endothelial cells." (PMID 34578436, 2021). "Since (LAG3+CD160+ CD8+)NKT cells were also positively correlated with the disease severity, suggesting that it may function as a double edge sword, playing both protective and pathogenic roles in the pathogenesis of COVID-19." (PMID 35281000, 2022). "Comparison between the disease conditions indicated significantly stronger expression of certain NK cell receptors (CD160, KLRC2, KLRC3, KLRF1, KIR3DL2, NCR1, NCR3) along the SLEC lineage in mild COVID-19 compared to severe COVID-19." (PMID 36591270, 2022). "In this study, (NCAM1+CD160+)NK cells increased significantly in all of the SARS-CoV-2 infected individuals compared to the HC and were positively correlated with the disease severity, suggesting that this NK cell subset may play both protective and pathogenic roles in the pathogenesis of COVID-19." (PMID 35281000, 2022). "In severe cases of COVID-19, the CD160 cluster was noticeable absent." (PMID 36034704, 2022). "A very recent study has also demonstrated the expansion of NKT CD160 cluster in moderate but not severe COVID-19 patients, which was believed to promote rapid control of the disease through direct cytotoxicity as well as mediating the antibody-dependent cell-mediated cytotoxicity effect." (PMID 33906918, 2021). "However, the NKT CD160 cluster was notably absent in severe COVID-19 cases." (PMID 34050887, 2022).
melanoma (10 papers, 2016 to 2024). A malignant, usually aggressive tumor composed of atypical, neoplastic melanocytes. "In this scenario, CD160 deficient NK cells showed in melanoma and RMA-S lymphoma tumor models a defect in tumor control due to impaired IFNγ production." (PMID 30483269, 2018). "Lastly, NCT04477876 is an observational study aiming to quantify CD160-TM/CD160-GPI expression in melanoma patients and to assess the therapeutic potential of anti-CD160-TM/CD160-GPI agonist mAbs." (PMID 37345056, 2023). "We established that melanoma cells expressed CD160-GPI and secreted sCD160 in their extracellular environment." (PMID 35428910, 2022). "We next aimed to determine if the synthesis of CD160 transcripts by melanoma cells was correlated with efficient protein expression." (PMID 35428910, 2022). "Our data therefore established that melanoma cells produced CD160-GPI and directly released its soluble form into the extracellular environment." (PMID 35428910, 2022). "By performing immunohistochemistry analyses, we observed a strong expression of CD160 at the primary cutaneous tumor site of melanoma patients." (PMID 35428910, 2022). "We further demonstrated that melanoma cells express CD160-GPI isoform and constitutively release the soluble form (sCD160) into the tumor environment." (PMID 35428910, 2022). "A co-stimulatory role for CD160 has been previously suggested in NK cells and T cells in the context of allograft rejection, melanoma and lymphoma tumor models." (PMID 30483269, 2018). "Our above data suggested that CD160-GPI is expressed by melanoma cells but not processed as a membrane-associated receptor in these cells." (PMID 35428910, 2022). "These first results prompted us to determine whether CD160 expression could be a characteristic of melanoma as well as its potential function in this skin tumor context." (PMID 35428910, 2022). "However, a positive signal was observed with the anti-CD160-GPI BY55 mAb following cell permeabilization, suggesting that CD160-GPI might be sequestered at the intracellular level in melanoma cells." (PMID 35428910, 2022). "Currently, the anti-CD160-TM antibody (NCT04477876) is undergoing clinical trials to assess its safety and efficacy for patients with inoperable stage III or IV melanoma." (PMID 38592036, 2024). "While blockade of PD-1 or PD-L1 in combination with IL PV-10 therapy led to anti-tumor immunity in murine melanoma, many CD8+ T cells infiltrating tumors express other co-inhibitory molecules including Tim3, Lag3, CD160, CD244 and BTLA." (PMID 29694419, 2018). "CD160 (cluster of differentiation 160), also known as natural killer cell receptor BY55, plays a role in human cancers such as chronic lymphocytic leukemia (CLL), colon cancer and melanoma, and pancreatic cancer." (PMID 35812748, 2022). "In a phase 1 trial of patients with melanoma patients and who received melanoma antigen recognized by T-cell 1 (MART1) peptide vaccinations with or without IMP321, those treated with IMP321 presented decreased expression of PD-1, LAG-3, TIM-3, CD244, and CD160." (PMID 37509517, 2023). "No expression of CD160-TM or CD160-GPI was detected at the cell surface of melanoma cell lines." (PMID 35428910, 2022). "Thus, CD160-GPI was found expressed on the endothelial cells of newly formed blood vessels in human colon carcinoma and in a mouse B16 melanoma model but not in vessels of healthy tissues." (PMID 35428910, 2022).
autoimmune disease (8 papers, 2019 to 2024). A disorder resulting from loss of function or tissue destruction of an organ or multiple organs, arising from humoral or cellular immune responses of the individual to their own tissue constituents. "Genetic studies have identified ethnic differences in gene polymorphisms of CD160 in autoimmune diseases and RAD51B in BC." (PMID 35812748, 2022). "Recent genetic studies have identified an association of CD160/HVEM/LIGHT/BTLA pathway-related genes with autoimmune diseases." (PMID 34238277, 2021). "Though our study indicated CD160 rs744877 locus is a susceptible factor for GD, the molecular mechanisms underlying the roles of CD160 rs744877 in autoimmune diseases are still unclear." (PMID 34238277, 2021). "The value of the combination of CD160 with previously established diagnostic methods in the diagnosis of common autoimmune diseases may be promising, and can be explored in future studies." (PMID 30842773, 2019). "In addition to its important role in the regulation of different immune cells, CD160 has been implicated in the pathophysiological processes of different diseases, including autoimmune diseases, atherosclerosis, retinal vascular diseases, and chronic viral infections." (PMID 36420268, 2022). "CD160 activates natural killer cells with specific domains, making it a novel therapeutic target in the fight against atherosclerosis, autoimmune diseases, and many cancers." (PMID 36733384, 2022). "In general, CD160 has been reported to be involved in the development of some pathologies, including autoimmune diseases, inflammatory diseases, atherosclerosis, retinal vascular diseases, chronic viral infections, and cancer." (PMID 36420268, 2022). "Some gene polymorphisms in the CD160/HVEM/LIGHT/BTLA pathway have an obvious influence on their functions and are thus associated with host susceptibility to autoimmune diseases.." (PMID 34238277, 2021). "RRA validation study also identified CD160 as the most significant gene aberrantly expressed in autoimmune diseases (Adjusted P = 5.9E-09)." (PMID 30842773, 2019). "RRA discovery study suggested that CD160 was the most significant gene aberrantly expressed in autoimmune diseases (Adjusted P = 5.9E-12), followed by CD58 (Adjusted P = 5.7E-06) and CD244 (Adjusted P = 9.5E-05)." (PMID 30842773, 2019). "For instance, several studies using animal models of autoimmune diseases proved the involvement of HVEM/CD160/BTLA/LIGHT pathway in the development of autoimmune diseases." (PMID 30842773, 2019). "This study suggests that CD160 is the most significant co-signaling gene aberrantly expressed in autoimmune diseases." (PMID 30842773, 2019). "In the RRA validation study, RRA analysis of those 6 RNA-seq datasets validated CD160 as the most significant gene aberrantly expressed in autoimmune diseases (Adjusted P = 5.9E-09)." (PMID 30842773, 2019). "Future studies are recommended to explore the feasibility of treating autoimmune diseases by targeting CD160-related pathway." (PMID 30842773, 2019). "This study suggests that CD160 is the most significant co-signaling gene aberrantly expressed in autoimmune diseases, and its dysfunction is an important characteristic of autoimmunity including GD." (PMID 30842773, 2019). "The RRA outcomes after ComBat normalization was similar with that before normalization, and CD160 was still the most aberrantly expressed co-signaling molecule in autoimmune diseases (adjusted P-value = 1.3E-11)." (PMID 30842773, 2019). "The findings from our study identify CD160 as a novel therapeutic target for the treatment of autoimmune diseases, which has important implications for future studies on CD160-related pathway." (PMID 30842773, 2019). "We further found that the aberrant expression of CD160 was statistically significant in multiple autoimmune diseases including GD (P < 0.05), and CD160 had a moderate role in diagnosing those autoimmune diseases." (PMID 30842773, 2019).